CHMP3 (charged multivesicular body protein 3)
Description:
Probable core component of the endosomal sorting required for transport complex III (ESCRT-III) which is involved in multivesicular bodies (MVBs) formation and sorting of endosomal cargo proteins into MVBs. MVBs contain intraluminal vesicles (ILVs) that are generated by invagination and scission from the limiting membrane of the endosome and mostly are delivered to lysosomes enabling degradation of membrane proteins, such as stimulated growth factor receptors, lysosomal enzymes and lipids. The MVB pathway appears to require the sequential function of ESCRT-O, -I,-II and -III complexes. ESCRT-III proteins mostly dissociate from the invaginating membrane before the ILV is released. The ESCRT machinery also functions in topologically equivalent membrane fission events, such as the terminal stages of cytokinesis and the budding of enveloped viruses (HIV-1 and other lentiviruses). ESCRT-III proteins are believed to mediate the necessary vesicle extrusion and/or membrane fission activities, possibly in conjunction with the AAA ATPase VPS4. Selectively binds to phosphatidylinositol 3,5-bisphosphate PtdIns(3,5)P2 and PtdIns(3,4)P2 in preference to other phosphoinositides tested. Involved in late stages of cytokinesis. Plays a role in endosomal sorting/trafficking of EGF receptor. Isoform 2 prevents stress-mediated cell death and accumulation of reactive oxygen species when expressed in yeast cells.
Synonyms: NEDF; VPS24; CGI-149
Tractability: Antibody: its Gene Ontology location is reachable by antibodies, with high confidence. PROTAC: UniProt records ubiquitination sites on it; ubiquitination databases record sites on it; its protein half-life has been measured.
Gene: Protein-coding gene on chromosome 2 (86,503,430 to 86,563,507, reverse strand). Ensembl gene ENSG00000115561.
Subcellular location: Cytoplasm, cytosol; Membrane; Endosome; Late endosome membrane
Pathways (Reactome):
Disease: Budding and maturation of HIV virion; HCMV Late Events; Translation of Replicase and Assembly of the Replication Transcription Complex
Autophagy: Late endosomal microautophagy; Macroautophagy
Cell Cycle: Sealing of the nuclear envelope (NE) by ESCRT-III
Programmed Cell Death: Pyroptosis
Vesicle-mediated transport: Endosomal Sorting Complex Required For Transport (ESCRT)
Gene Ontology:
Molecular function: membrane bending activity; molecular function inhibitor activity; phosphatidylcholine binding; protein binding; ubiquitin-specific protease binding; phosphatidylinositol-4,5-bisphosphate binding
Biological process: autophagosome maturation; autophagy; late endosome to lysosome transport; membrane fission; midbody abscission; mitotic metaphase chromosome alignment; multivesicular body sorting pathway; multivesicular body-lysosome fusion; nuclear membrane reassembly; nucleus organization; plasma membrane repair; protein polymerization; regulation of centrosome duplication; regulation of early endosome to late endosome transport; regulation of exosomal secretion; regulation of mitotic spindle assembly; suppression of viral release by host; ubiquitin-dependent protein catabolic process via the multivesicular body sorting pathway; viral budding from plasma membrane; viral budding via host ESCRT complex; viral release from host cell; late endosome to vacuole transport; macroautophagy; multivesicular body assembly; vesicle fusion with vacuole; and 4 more
Cellular component: amphisome membrane; autophagosome membrane; cytoplasmic vesicle; ESCRT III complex; extracellular exosome; kinetochore; kinetochore microtubule; late endosome; lysosomal membrane; midbody; multivesicular body membrane; nuclear pore; plasma membrane; cytosol; early endosome; endosome; late endosome membrane; membrane
Genetic constraint (gnomAD): Loss-of-function variants: 8 observed, 26.58 expected, observed/expected ratio (o/e) 0.3, 90% interval 0.18 to 0.54. The upper end of that interval is the gene's LOEUF score, 0.54, which puts it in group 2 of 6, group 1 being the genes least tolerant of losing a copy. Missense variants: 207 observed, 270.77 expected, observed/expected ratio (o/e) 0.76, 90% interval 0.68 to 0.86. Synonymous variants: 86 observed, 85.63 expected, observed/expected ratio (o/e) 1, 90% interval 0.84 to 1.2.
Homologues: Orthologues: chimpanzee CHMP3 (99% identical), dog CHMP3 (97% identical), mouse Chmp3 (97% identical), guinea pig CHMP3 (96% identical), rat Chmp3 (96% identical), pig CHMP3 (92% identical), tropical clawed frog chmp3 (85% identical), zebrafish chmp3 (83% identical), Drosophila melanogaster Vps24 (61% identical), Caenorhabditis elegans vps-24 (56% identical). Paralogues in human: CHMP2A (26% identical), CHMP2B (26% identical), CHMP1B (18% identical), CHMP1A (14% identical).
Diseases named in the same sentence as CHMP3 in open-access papers:
CHMP3 is named in the same sentence as 24 diseases in open-access papers, as found by Europe PMC text mining. Sharing a sentence is not in itself a finding about the gene and the disease. The quoted sentences say what the papers report.
breast cancer (4 papers, 2022 to 2024). A primary or metastatic malignant neoplasm involving the breast. "CHMP3 is a tumor suppressor with lost expression across a wide range of human cancers and its high level predicts a favorite survival outcome of breast cancer patients." (PMID 35768804, 2022). "High CHMP3 expression in breast cancer patients predicts better survival outcomes." (PMID 37008939, 2023).
COVID-19 (2 papers, 2023). A disease caused by infection with severe acute respiratory syndrome coronavirus 2. "Analysis of the combined cohorts revealed elevated autoantibody responses against SPANXN4, STK25, ATF4, PRKD2, and CHMP3 proteins in COVID-19 patients." (PMID 37520825, 2023).
triple-negative breast carcinoma (2 papers, 2020 to 2023). An invasive breast carcinoma which is negative for expression of estrogen receptor (ER), progesterone receptor (PR), and human epidermal growth factor receptor 2 (HER2). "MiR-122-5p promotes aggression and epithelial–mesenchymal transition in triple-negative breast cancer, by suppressing charged multivesicular body protein 3 (CHMP3) through mitogen-activated protein kinase (MAPK) signaling." (PMID 36851037, 2023). "MiRNA-122-5p stimulates the aggression and epithelial-mesenchymal transition (EMT) in triple-negative breast cancer by negative regulation of CHMP3." (PMID 33231565, 2020).
diabetes (1 paper, 2026). "At the mRNA level only borderline significant changes in Chmp3 and Fubp3 were detected using the duodenum of the pre-clinical high-fat diet C57BL/6J mouse model of pre-diabetes." (PMID 41840478, 2026).
gastric adenocarcinoma (1 paper, 2025). "Using data from 407 gastric adenocarcinoma patients in the TCGA database, we examined the prognostic impact of necroptosis-related gene CHMP3." (PMID 41249133, 2025).
lung squamous cell carcinoma (1 paper, 2023). "TMEM120B, HMOX2, CALCOCO2, LONP2, ZNF440, CLCC1, and CHMP3 were identified to be optimal prognostic factors for lung squamous cell carcinoma (LUSC)." (PMID 36999050, 2023).
lymph node metastasis (1 paper, 2025). "We observed that the expression of necroptosis-related gene CHMP3 was significantly associated with lymph node metastasis." (PMID 41249133, 2025). "Univariate logistic regression analysis indicated that high expression of CHMP3 was significantly associated with lymph node metastasis (OR = 1.934, 95% CI: 1.223–3.058; P = 0.005)." (PMID 41249133, 2025). "In particular, although a significant correlation between CHMP3 expression and lymph node metastasis was observed in both TCGA data and our paired immunofluorescence samples, it is critical to note that these data indicate an association rather than causality." (PMID 41249133, 2025).
Spastic paraplegia (1 paper, 2022). Complete loss of the ability to move the lower limbs accompanied by spasticity of the lower limbs. "Finally, a CHMP3 mutation, T173I, located within the MIM used in our binding studies, is associated with spastic paraplegia, a disease associated with SPASTIN defects." (PMID 36107470, 2022).
tumor (13 papers, 2022 to 2025). "Spatial transcriptomic analysis also revealed specific enrichment of CHMP3 at the tumor–immune interface, implying a potential role in immune cell recruitment or polarization." (PMID 41249133, 2025). "Necroptosis-related protein CHMP3 expression exhibited a gradual increase from normal tissue to primary tumor and further to metastatic lymph nodes." (PMID 41249133, 2025). "Moreover, immunohistochemistry revealed significant high expression of CHMP3 in tumor liver tissue." (PMID 37008939, 2023). "The mCherry-labeled CHMP3 was located on the cell membrane and formed microvesicles to fix the pores and help the cell membrane repair during VNP-GD-triggered tumor pyroptosis." (PMID 36280674, 2022). "Similarly, CHMP3 and CHMP2A show increased expression in HCC tissue samples, thus potentially influencing tumor progression." (PMID 40918134, 2025).
cancer (8 papers, 2013 to 2025). A tumor composed of atypical neoplastic, often pleomorphic cells that invade other tissues. "Low CHMP3 expression is associated with a poor prognosis in some cancer types; high CHMP3 expression may indicate improved patient survival." (PMID 39590305, 2024). "Some genes exhibited positive regulation in particular cancer types, including VPS37C in DLBC and CHMP3 and VPS37B in TGCT, which were positively correlated with immune cell enrichment." (PMID 40230849, 2025). "Meanwhile, CHMP3 and CHMP4C were significantly stained in normal renal tissues, and the staining range was small in cancer tissues." (PMID 35845137, 2022). "Importantly, a number of studies have shown changes in expression of ESCRT components in human cancer cells, including changes in expression of ESCRT-I components Tsg101 and Vps37A and ESCRT-III components Chmp1A and CHMP3." (PMID 23418496, 2013).
infection (6 papers, 2011 to 2025). The state of being infected such as from the introduction of a foreign agent such as serum, vaccine, antigenic substance or organism. "Combining the dual-color reporter approach with quantitative flow cytometry, we found that SM removal enhances vacuole disruption and cytosolic release of Salmonella during host cell infection to a similar degree as loss of CHMP3, an essential subunit of the ESCRT-III complex." (PMID 35388011, 2022). "So, CHMP3 was silenced in A549 cells and α3 integrin levels were analyzed after 24 h infection with P. brasiliensis." (PMID 37755020, 2023). "However, silencing of TSG101, CHMP3, VPS4B, or ALIX—components of the ESCRT pathway that control MVB biogenesis—has been shown to impair the infection and entry of CCHFV, indicating that ESCRT plays a role in CCHFV entry." (PMID 40996032, 2025).
CHMP3 also shares sentences with these, for which no sentence is quoted: liver cancer (3 papers); co-infection (1); colorectal cancer (1); diabetic foot ulcer (1); Down syndrome (1); gastric cancer (1); glioma (1); infectious disease (1); lung carcinoma (1); motor neuron diseases (1); neurodegenerative disease (1); neuropathy (1); virus infection (1).